IGF1 (insulin like growth factor 1)
Diseases named in the same sentence as IGF1 in open-access papers (continued):
Sharing a sentence is not in itself a finding about the gene and the disease.
breast cancer (continued). "Our data suggest that breast cancer patients maintain significantly higher concentrations of IGF-1 during the perioperative period." (PMID 38067195, 2023). "Eleven hematological and biochemical markers were found to be associated with breast cancer risk, among which higher serum levels of CRP, testosterone, and IGF-1 were also associated with a higher breast cancer mortality." (PMID 38000092, 2023). "In breast cancer, miR-186 potently blocks the epithelial-mesenchymal transition, and in neuroblastoma cells, the IGF1 expression is reduced by miR-186." (PMID 37324202, 2023). "CRP, testosterone, and IGF-1 were found to have different impacts on the transitions of different breast cancer states, confirming the role of chronic inflammation and endogenous hormones in breast cancer progression." (PMID 38000092, 2023). "As IGF1 has long been implicated in various tumorigeneses, including pancreatic cancer, breast cancer, Ewing sarcoma, and melanoma, several small molecules and monoclonal antibodies targeting IGF1 signaling have been developed." (PMID 37731513, 2023). "In fact, the alteration of IGF-1 signaling has a crucial role in the antineoplastic effects of CR, according to preclinical investigations in colon, pancreatic, and breast cancers." (PMID 38202341, 2023). "Proteomic screening and network analyses of breast cancer cell lines stimulated with either IGF-1 or insulin suggested signaling interactions between the two pathways." (PMID 36568144, 2022). "At a six-hour time point, there was a substantial increase in nuclear SRPK2 upon IGF-1 exposure in both breast cancer cell lines, which was abrogated upon rapamycin treatment." (PMID 36096767, 2022). "When soluble klotho was applied to the breast cancer cells, the activation of insulin and IGF-1 pathway, resulting in reduced proliferation, was identified." (PMID 35666743, 2022). "Circulating levels of IGF-1 and its binding protein, IGFBP3, have been linked to breast cell proliferation and breast cancer risk." (PMID 36672557, 2022). "In breast cancer, IGF-1 regulates cell growth through stimulation of the insulin growth factor receptor (IGF-1R), which consequently phosphorylates either insulin receptor substrate-1 (IRS-1) or insulin receptor substrate-2 (IRS-2)." (PMID 35366286, 2022). "In human breast cancer, klotho is known to suppress tumor growth by inhibiting the IGF-1 pathway and increasing the activation of the FGF pathway." (PMID 35666743, 2022). "Our findings showed that variants of energy homeostasis genes modified the association between the IGF-1 or IGFBP-3 serum concentration and breast cancer risk in premenopausal women." (PMID 35115550, 2022). "IGF1 synergizes with estrogen to promote the proliferation of breast cancer cells and increase their metastatic potential." (PMID 35463082, 2022). "Similar to our results, Amy Lyons and co-workers demonstrated that in breast cancer cells IGF-1 facilitated mitochondrial biogenesis and potential through induction of PGC-1β and PRC." (PMID 35334906, 2022). "In summary, the present study demonstrates that GASP1 is highly expressed in breast cancers, and plays an oncogenic role in breast cancer cells by forming a positive feedback loop with IGF1/IGF1R pathway." (PMID 36042202, 2022). "Studies have shown that elevated circulating levels of IGF-1 and reduced levels of IGFBP-3 are associated with an increased risk of premenopausal breast cancer." (PMID 36482346, 2022). "furthermore, the IGF-1Rβ levels are increased in breast cancer metastasis and disruption of IGF-1/IGF-1R signaling inhibited tumorigenesis in preclinical models." (PMID 35372035, 2022). "There are three systems involved in the connection of adipose tissue and breast cancer: steroidal sex hormones, adipokines, and insulin-like growth factor 1, (IGF-1)." (PMID 35989732, 2022).
breast cancer (continued). "Lower expression levels of five hub gens, including IGF1, LEP, ADIPOQ, NR3C1, and PPARG, were determined and were remarkably associated with poorer OS and BCSS among breast cancer patients." (PMID 35317079, 2022). "A phase II study of another IGF-1/2 neutralizing monoclonal antibody, dusigitumab, in combination with an AI in ER+ breast cancer is yet to report." (PMID 36046843, 2022). "An elegant study with spontaneous dwarf rats which lack GH and have very low IGF1 levels shows that the growth of N-methyl-N-nitrosourea-induced mammary tumors fully depends on GH injections." (PMID 35966052, 2022). "The aim of this study was to assess the modifying effect of the genetic variation in some energy homeostasis genes on the association of serum concentrations of IGF-1 and IGFBP-3 with breast cancer risk." (PMID 35115550, 2022). "For example, EPL120 showed dose-dependent inhibition of the (exogenous) IGF-1 stimulated growth in cell numbers of MCF 7 human breast cancer cells over 72h across the EPL120 dose range 0.04 nM– 4 μM." (PMID 36454864, 2022). "The results showed that CXCL12, ESR1, IGF1, and FOS were significantly associated with the survival of breast cancer." (PMID 35463082, 2022). "Other biomarkers such as BMI, neutrophil count, IGF-1, testosterone and sex hormone-binding globulin (SHBG) were also associated with breast cancer risk, but the ORs were below 1.2." (PMID 35578620, 2022). "Meanwhile, IGF1 increases GASP1 expression via a PI3K/AKT pathway-dependent manner to thereby form a vicious feedback loop propelling the progression of breast cancer and decreasing sensitivity to paclitaxel." (PMID 36042202, 2022). "As known, an increment of insulin and the IGF-1 are related to cancers, such as breast cancer and colon cancer." (PMID 35299970, 2022). "We further investigated the subcellular localization of phosphorylated SRPK2 upon IGF- 1 exposure by performing cell fractionation in which breast cancer cells were treated with a vehicle or rapamycin and exposed to IGF-1." (PMID 36096767, 2022). "The expression of insulin-like growth factor-1 (IGF-1) is higher in the sera of breast cancer patients than in those of benign tumour patients." (PMID 36482346, 2022). "The current study aimed to investigate angiopoietin-like protein 4 (ANGPTL4) and insulin-like growth factor-1 (IGF-1) protein expression in breast tissue from young patients with breast carcinoma." (PMID 35366286, 2022). "Breast carcinoma cell lines exhibit more aggressive, migratory behavior when stimulated with IGF-1 or when overexpressing IGF-1R in vitro, while knockdown of IGF-1R expression impairs colony formation and invasion." (PMID 36556357, 2022). "IGF-1 promotes breast carcinoma cell migration through the formation of lamellipodia and focal adhesions." (PMID 36556357, 2022). "Breast carcinoma cells stimulated with IGF-1 have decreased expression of the epithelial marker E-cadherin and increased expression of the mesenchymal marker vimentin and adopt a fibroblast-like, mesenchymal morphology." (PMID 36556357, 2022). "In this cross-sectional study we investigated the expression of ANGPTL-4 and IGF-1 in primary breast carcinoma tissue samples from young age patients ≤45 years." (PMID 35366286, 2022). "H19, NR2F1-AS1, and SNHG7 participate in the development of melanoma and breast cancer through modulation of IGF1." (PMID 33768092, 2021). "For example, one study reported that lncRNA nuclear receptor subfamily 2 group F member 1 antisense RNA 1 (NR2F1-AS1) promoted angiogenesis in breast cancer by activating the insulin-like growth factor 1 (IGF-1)/IGF-1 receptor/ERK signaling pathway." (PMID 34738863, 2021). "In line with our previously published data in a subset of patients with HR+ breast cancer (n = 24), metabolic evaluations performed in the whole patient cohort showed a significant reduction of circulating levels of c-peptide, IGF1 and leptin after the FMD." (PMID 34439167, 2021).
breast cancer (continued). "The effect of GH on breast cancer cells can be through IGF-1 or proliferative effect independent from IGF-1." (PMID 34530525, 2021). "This study confirms associations of testosterone, IGF-1 and SHBG with breast cancer risk, with heterogeneity by menopausal status for testosterone." (PMID 33864017, 2021). "In breast cancer cells, E-cadherin downregulation hyperactivates IGF1R/IR signaling, thus enhancing sensitivity of breast cancer cells to IGF1 stimulation and Akt or ERK phosphorylation." (PMID 33673232, 2021). "Extracellular AGR2 (eAGR2) is found to act synergistically with insulin-like growth factor-1 (IGF-1) to induce cell proliferation, migration, and epithelial–mesenchymal transition in breast cancer cells." (PMID 34679944, 2021). "The endogenous factors which the increased expression stimulates in the development of breast cancer are as follows: IGF1, PI-9, ERα, BRF2, cyclin D1, pS2, TGF-β3, monoamine oxidase A, and α-antichymotripsin." (PMID 34462889, 2021). "In a murine model of breast cancer, ASCs enhance breast cancer proliferation through secretion of IGF-1." (PMID 34912237, 2021). "Elevated levels of insulin-like growth factor 1 (IGF1) and excessive IGF1R signaling have been implicated in an increased risk of breast cancer." (PMID 34441794, 2021). "A growing body of evidence leads to the important role of the IGF1 system in breast cancer development, progression and metastasis." (PMID 34157951, 2021). "IGF-1 can also regulate GPER expression in ER+ breast cancer cells through the IGF-IR/ERK/c-fos/AP1 transduction pathway." (PMID 33816477, 2021). "We experimentally validated the last prediction by chemically inhibiting ribosomal protein S6 kinase in breast cancer cells and then treating them with IGF1 and insulin, as described in Methods." (PMID 34191793, 2021). "Its depletion abolishes AKT and ERK phosphorylation downstream of IGF-1 and inhibits breast cancer cell proliferation." (PMID 33991522, 2021). "In obese post-menopausal women, there are increased levels of plasma insulin and insulin-like growth factor-1 (IGF-1) that have mitogenic effects on breast cancer cells." (PMID 33482868, 2021). "A recent report indicates that the lncRNA NR2F1-AS1 promotes breast cancer angiogenesis via sponging miRNA 338-3p, thereby enhancing IGF1 expression and activating IGF1R signaling." (PMID 33673232, 2021). "To further confirm that CT45A is a direct downstream gene of the AKT pathway, we treated breast cancer cells with the AKT pathway activator IGF-1 and found that the IGF-1 treatment leads to CT45A induction." (PMID 34503444, 2021). "In preclinical breast cancer models, the IGF1/IGF1R/Akt axis sustained mRNA expression of EphB4, thereby promoting cell proliferation and migration responses, which were sentitive to the PI3K inhibitor LY294002." (PMID 34440844, 2021). "By studying signaling in the earlier time points, we hope to unravel some early response differences of the breast cancer cells to single IGF1 or insulin stimulation." (PMID 34191793, 2021). "Regarding the remaining proteins, HGF, GRO-1, and IGF-1 have been found to stimulate the adhesion of breast cancer, gastric cancer, and multiple myeloma cells, respectively; in all these studies, the activity of these proteins was dependent on β1-integrin." (PMID 33921783, 2021). "High levels of circulating IGF-1 and IGFBP-3 in the blood are related to a higher risk of certain cancers, such as colorectal, prostate, and breast cancers." (PMID 34444753, 2021). "It was further shown that bisphosphonates inhibit the vascular endothelial growth factor (VEGF)-mediated angiogenesis of breast cancer cells via suppression of the IGF-1/AKT/HIF-1α/VEGF axis." (PMID 34064589, 2021). "Vitamin D and its analogs have also been shown to suppress IGF-1-induced growth of breast cancer cells by downregulating IGF and IGF-1R and increasing IGF-BP expression." (PMID 35008602, 2021).
breast cancer (continued). "Over the last two decades, many studies have demonstrated that the insulin-like growth factor-1 (IGF-1) is involved in a number of patho-physiological processes, as well as in the development of different types of solid tumors, including breast cancer (BC)." (PMID 33829018, 2021). "Overall, the association between IGF-1, metabolic variables, and clinical outcomes in HER2-amplified early breast cancer population hasn't been well-understood." (PMID 32391265, 2020). "Evidence suggests Insulin-like growth factor 1 (IGF1) signaling is involved in the initiation and progression of a subset of breast cancers by inducing cell proliferation and survival." (PMID 32444795, 2020). "This review highlights the different mechanisms by which cytokines, IGF-1, and IGFBP-3 levels increase the risk of developing breast cancer." (PMID 32528752, 2020). "In this context, we have recently provided evidence that the capacity of a specific IGF1R antibody to block IGF1-mediated IGF1R activation was impaired in mutant BRCA1-expressing breast cancer cells." (PMID 32391121, 2020). "It is well-known that IGF1 is a key growth factor in mammary gland formation during development, however, it also plays important role in breast cancer." (PMID 32133294, 2020). "It has been demonstrated that the hyperactivation of Insulin/IGF-1 pathway due to “diabesity” condition (obesity concomitant with insulin resistance, hyperinsulinemia and/or hyperglycemia) mediates breast cancer progression." (PMID 32132979, 2020). "The stimulation of an ER-positive breast cancer cell line (MCF7) with IGF-1 led to the identification of an IGF-1 gene signature, which was enriched for signaling pathways that are involved in mitogenesis such as ER, Ras/ERK1/2, and PI3K/Akt/mTOR." (PMID 33604295, 2020). "Estrogen enhances the effect of IGF-1 levels on breast cancer cell growth and modulates the effect of IGFBP-3 levels on premenopausal breast cancer risk." (PMID 32528752, 2020). "In our study, lncRNA NR2F1‐AS1 induced expression of IGF‐1 in breast cancer cells, which then increased the phosphorylation of IGF‐1R and ERK1/2 in HUVECs." (PMID 32548873, 2020). "Exercise training has a significant physiological effect on IGF-1 in postmenopausal breast cancer survivors, and high-intensity interval training shows a remarkable effect on the expression of microRNAs in breast cancer patients undergoing hormone therapy." (PMID 33108715, 2020). "Our findings suggest the important role of circulating higher levels of IGF1 as a protective predictor of mortality after breast cancer." (PMID 32974138, 2020). "Because SNHG7 is highly expressed, robustly regulated by IGF1 signaling, and is altered in a subset of breast cancer patients that correlate with survival, it was investigated further." (PMID 32444795, 2020). "Women with early breast cancer had 21% higher IGF-1 and 19% higher IGFBP-3 than unaffected women, however IGF-1 levels were negatively associated with age (and also BMI) across all groups." (PMID 33597950, 2020). "First, note that the top-ranking node IGF1 in this pathway indeed is known to have crosstalk with estrogens; anti-estrogens such as tamoxifen have served as a routine treatment for breast cancer in many countries." (PMID 32164570, 2020). "Currently, the dual IGF1/2-neutralizing antibody xentuzumab in combination with everolimus and exemestane is subject to clinical trial in ER+/ErbB2- breast cancer." (PMID 32493414, 2020). "We detected that ASC.B6 enhanced the in vitro proliferation of 4T1 murine breast cancer cells in an IGF1-dependent manner." (PMID 32133294, 2020). "Insulin-like growth factor 1 (IGF-1) and binding protein 3 (IGFBP-3) are associated with breast cancer in women at average risk of cancer." (PMID 33092613, 2020).
breast cancer (continued). "Mechanically, lncRNA NR2F1‐AS1 increased insulin‐like growth factor‐1 (IGF‐1) expression through sponging miRNA‐338‐3p in breast cancer cells and then activated the receptor of IGF‐1 (IGF‐1R) and extracellular signal‐regulated kinase (ERK) pathway in HUVECs." (PMID 32548873, 2020). "IGF1 is crucial during mammary gland development; however, it also plays important role in breast cancer." (PMID 32133294, 2020). "Klotho was proposed to be implicated in aging through inhibition of the Insulin-like Growth Factor 1 (IGF-1) pathway, but it also functions as a tumor suppressor in several types of cancer, including breast cancer." (PMID 31936350, 2020). "Given that we have found upregulated IGF1 production by polyploid ASCs, which promoted breast cancer cell proliferation in vitro, we aimed to confirm the tumor-promoting function of these stem cells and to clarify the underlying mechanism." (PMID 32133294, 2020). "Here, we demonstrate through whole transcriptome RNAseq that IGF1 signaling regulates a subset of lncRNAs that are altered in breast cancer, including the known but unstudied lncRNA, SNHG7, which is amplified or overerxpressed in ~5% of breast tumors in TCGA." (PMID 32444795, 2020). "Intriguingly, in HER2+ breast cancer patients, high IGF-1 in normal weight patients showed a superior recurrence free survival compared to low IGF-1." (PMID 33339340, 2020). "IGF-1 receptor (IGF-1R) expression correlates with poor survival and is thought to have a possible role as a prognostic marker, with higher concentrations of IGF-1 noted in the serum of breast cancer patients." (PMID 32792532, 2020). "Three quarters of breast cancer patients show activation of insulin/IGF-1 signaling and this rises to 87% in patients with invasive breast cancer." (PMID 33339340, 2020). "In many cancers, the studies of expression and mechanisms of action of IGF1 splice isoforms are only based on in vitro models (e.g., breast cancer, endometrial cancer, osteosarcoma, myelogenous leukemia, or melanoma)." (PMID 32977489, 2020). "Insulin-like growth factor (IGF-1) and its primary binding protein (IGFBP-3) are known risk factors for breast cancer due to their ability to stimulate mitosis and suppress programmed cell death." (PMID 33092613, 2020). "The underlying mechanism was uncovered that lncRNA NR2F1 sponged miRNA‐338‐3p to induce IGF‐1 in breast cancer cells, which further activated IGF‐1R and ERK pathway in HUVECs." (PMID 32548873, 2020). "In this regard, the portrait of genetic alterations in breast cancer support a dysfunction of the IGF-1/IGF-1R system leading to the development of various breast malignancies, including TNBC." (PMID 32325700, 2020). "In our previous study, we have shown that murine ASCs, which undergo polyploidization during their prolonged in vitro culturing, enhanced the proliferation of 4T1 murine breast cancer cells in IGF1 dependent manner." (PMID 32133294, 2020). "Alterations in the IGF-1/IGF-1R-mediated signaling have been associated with the development and progression of hormone-related tumors, including breast cancer." (PMID 32325700, 2020). "In summary, the serological and hormonal profile of obese MTB/TAN mice suggests the adipokine and insulin/IGF-1 signaling pathways as potential mediators of a relationship between obesity and breast cancer recurrence in this model." (PMID 30867005, 2019). "A randomized controlled trial of postmenopausal breast cancer survivors found that aerobic exercise decreased IGF-1 and insulin-like growth factor-binding protein-3 (IGFBP-3), a predominant binding protein for IGF-1." (PMID 31816813, 2019). "Biochemical and molecular dissection of the mechanisms of action of insulin and IGF1 in breast cancer will be of major translational impact." (PMID 31771180, 2019).